KEAP1 (kelch like ECH associated protein 1)
Diseases named in the same sentence as KEAP1 in open-access papers (continued):
Sharing a sentence is not in itself a finding about the gene and the disease.
pancreatic cancer (40 papers, 2011 to 2025). "Recent studies have evidenced that KRAS-driven lung and pancreatic cancer with KEAP1 or NRF2 mutations are highly dependent on glutaminolysis and are vulnerable to glutaminase inhibition." (PMID 38830868, 2024). "Although mutations in NRF2 (NFE2L2) or KEAP1 are uncommon in pancreatic cancer, NRF2 expression levels have been reported to be elevated in over 93% of PDAC." (PMID 36765792, 2023). "In pancreatic cancer, overexpressed ataxia-telangiectasia group D-associated gene products bind to KEAP1, leading to NRF2 activation." (PMID 35053572, 2022). "Instead, Keap1 expression associated in cell membranes had a significant protective effect on survival in multivariate analysis, with median pancreatic cancer-specific survival more than doubled." (PMID 25879528, 2015). "Membranous Keap1 expression associated with better relapse-free survival (p = 0.041) and also with longer pancreatic cancer-specific survival (PCSS) (median survival 14 vs. 32 months; p = 0.029)." (PMID 25879528, 2015). "Pharmacological manipulation of the Nrf2/Keap1 signalling pathway has the potential to reduce the rate of growth of primary pancreatic tumors, and render them more susceptible to attack by chemotherapeutic agents." (PMID 21489257, 2011). "Previous studies demonstrated that esculetin could bind to cytoplasmic Kelch-like ECH associated protein 1 (Keap1) to promote the nuclear translocation of Nrf2 in pancreatic cancer cells." (PMID 33080936, 2020). "Because Keap1 is often deleted and mutated in pancreatic cancer cells, which also causes the aberrant activation of Nrf2, disrupting the Keap1-Nrf2 binding for reactivating Nrf2 could not be an effective strategy for PC therapy." (PMID 31511020, 2019). "However, there is few study on the accurate detection of mutations in Keap1 and Nrf2 in pancreatic cancer, and the detailed investigations on these mutations are urgently needed." (PMID 31511020, 2019). "Moreover, somatic mutations of NRF2 and its regulator Kelch-like ECH-associated protein 1 (KEAP1) have been reported to be highly correlated with poor prognosis in type II pRCC and pancreatic cancer." (PMID 31357507, 2019). "Thus we propose that in pancreatic cancer cells there is a loss of interaction between Nrf2 and KEAP1 on exposure to esculetin that ultimately depletes ROS and abrogate NF-κB activity." (PMID 27756327, 2016). "In pancreatic carcinomas only synonymous mutations of Keap1 have been reported but interestingly in the context of pancreatic cancer biology, Keap1 mutations in other cancers seem to be more considerably prevalent in adenocarcinomas and in patients with smoking history." (PMID 25879528, 2015). "Membranous Keap1 associated with longer relapse-free survival (p = 0.041) and pancreatic cancer-specific survival (median survival 14 vs. 32 months; p = 0.029) and was in multivariate analysis an independent prognostic factor of pancreatic cancer-related death (HR 2.66, 95%CI 1.23-5.75)." (PMID 25879528, 2015). "Meanwhile, ferroptosis inducers promoted p62 accumulation and recruited Keap1 into p62 bodies in pancreatic cancer cells." (PMID 38994016, 2024). "The association between glutamine deprivation, NRF2/KEAP1, and cytokine secretion in KRAS-mutant pancreatic cancer warrants further investigation." (PMID 36942991, 2023). "For example, Costello and colleagues reported that UHRF1 maintains KEAP1 promoter methylation, thus regulating the Nrf2 pathway in pancreatic cancer." (PMID 36166308, 2022). "Esculetin can inhibit the proliferation of pancreatic cancer cells to modulate their apoptosis by enhancing KEAP1 activity." (PMID 36199579, 2022).
pancreatic cancer (continued). "Established murine pancreatic cancer cell lines from Keap1-null, Nrf2+/− KPC mouse pancreatic cancer cells showed increased nuclear accumulation of Nrf2." (PMID 35053572, 2022). "Esculetin (ESC) can bind to Keap1 to promote the dissociation and the accumulation of Nrf2 in the nucleus, thereby inhibiting the growth of pancreatic cancer cells." (PMID 36408214, 2022). "We established cell lines expressing constitutively activated Nrf2 or with Keap1/Nrf2 deletion from these pancreatic cancer tissues using a pre-established protocol." (PMID 33672789, 2021). "In contrast to the protective impact of Nrf2 on oxidative stress-induced carcinogenesis, a great number of studies have demonstrated a supporting role of the Keap1-Nrf2 pathway in pancreatic cancer development." (PMID 35052602, 2021). "Sestrin2 overexpression increased the protein expression of p-Nrf2, HO-1, and NQO-1 in pancreatic cancer cells compared with that in the control group, and the expression of the Nrf-2 binding protein Keap1 decreased." (PMID 34306067, 2021). "The authors have suggested that esculetin binds to Keap1 and inhibits its interaction with Nrf2 in pancreatic cancer cells." (PMID 35052602, 2021). "In a recent study, MBD1 (methyl-CpG-binding domain protein 1), a protein highly expressed in pancreatic cancer, was found to downmodulate KEAP1 expression by influencing the methylation status of its promoter." (PMID 31097977, 2019). "Analogous observations of Keap1 protein overexpression and better survival have been reported from pancreatic cancer and from squamous non-small-cell lung carcinoma." (PMID 29348788, 2017). "Depletion of Keap1 alone led to a substantial increase in the growth of pancreatic cancer cells, whereas depletion of UHRF1 alone led to a reduction." (PMID 26497117, 2016). "Mechanistically, depletion of UHRF1 reduced global and tumour suppressor promoter methylation in pancreatic cancer cell lines, and KEAP1 gene promoter methylation was reduced in one of three cell lines examined." (PMID 26497117, 2016). "We propose that esculetin binds to KEAP1 and inhibits its interaction with Nrf2 in pancreatic cancer cells." (PMID 27756327, 2016). "Taken together, these data indicate that UHRF1 promotes the growth of pancreatic cancer cells by reducing Keap1 levels and inducing activation of Nrf2." (PMID 26497117, 2016). "According to our knowledge, there is only one previous study evaluating Keap1 expression in pancreatic cancer in humans." (PMID 25879528, 2015). "The aim of this study was to evaluate the expression and possible prognostic role of Keap1 and 8-OHdG in pancreatic cancer." (PMID 25879528, 2015). "In order to investigate the integrity of the Nrf2/Keap1 system in pancreatic cancer, we first examined the protein expression levels of Keap1 and Nrf2 across a panel of five human pancreatic cancer cell lines." (PMID 21489257, 2011). "Taken together, these results indicate that post-translational factors contribute to the dysregulation of the Nrf2/Keap1 system in a subset of pancreatic cancer cell lines." (PMID 21489257, 2011). "Following our delineation of the Nrf2/Keap1 system in pancreatic cancer cell lines, we examined the expression levels of Nrf2 and Keap1 in human pancreatic tumor tissues, using immunohistochemistry." (PMID 21489257, 2011). "The Nrf2/Keap1 system appears to be dysregulated, yet functional, in certain pancreatic cancer cell lines, and in primary pancreatic ductal adenocarcinomas." (PMID 21489257, 2011). "Thus, in the next section, we give a comprehensive overview of the dual roles of the Keap1-Nrf2 pathway in pancreatic cancer." (PMID 35052602, 2021). "To clarify whether Nrf2 activation has similar effects in pancreatic cancer, we established mouse pancreatic cancer cell lines harboring Keap1 deletion, which resulted in the constitutive activation of Nrf2." (PMID 33672789, 2021). "The deletion of KEAP1 pancreatic tumor model leads to pancreatic atrophy." (PMID 33477494, 2021).
pancreatic cancer (continued). "Both KC::Keap1 and KPC::Keap1 mice contain constitutively activated Nrf2 due to Keap1 deletion, which does not promote the development of pancreatic cancer but causes the progressive atrophy of pancreatic parenchyma." (PMID 31511020, 2019). "As observed above, dCK regulates the Keap1/NRF2/ARE axis in pancreatic cancer cells." (PMID 29701272, 2018). "Thus, loss of UHRF1 is accompanied by an increase in cellular oxidative stress, suggesting that UHRF1, through the suppression of Keap1 expression, activates Nrf2, which protects pancreatic cancer cells from oxidative stress." (PMID 26497117, 2016). "We next turned our attention to the KEAP1 promoter, asking whether the KEAP1 gene promoter is silenced through methylation in pancreatic cancer cell lines." (PMID 26497117, 2016). "Oxidative stress and main redox regulators may participate in pancreatic carcinogenesis and Keap1 appears as a promising prognostic factor in pancreatic cancer." (PMID 25879528, 2015). "Here we have investigated the integrity of the Nrf2/Keap1 system in pancreatic cancer." (PMID 21489257, 2011). "Interestingly, the simultaneous activation of Kras and Nrf2 by Kras mutation and Keap1 deletion, respectively, did not promote pancreatic cancer development but led to pancreatic atrophy." (PMID 35052602, 2021). "The KEAP1/NRF2 axis also participates in the ferroptosis process in ischemic flap survival, renal cell carcinoma, and pancreatic cancer." (PMID 41356483, 2025). "These cell lines were more sensitive to CB-839 treatment than Keap1-null and Nrf2-null KPC mouse pancreatic cancer cell lines." (PMID 35053572, 2022). "Immunoblotting results indicated that KEAP1 levels were downregulated, while NRF2 levels were increased to some extent in pancreatic cancer cells treated with kaempferol." (PMID 33845796, 2021). "UHRF1 expression was observed in 20% (5 of 25) of benign pancreatic ducts compared to 86% (114 of 132) of pancreatic tumours, and an inverse relationship between UHRF1 and Keap1 levels in PDAC tumours (n = 124) was apparent (p = 0.002)." (PMID 26497117, 2016). "Our data suggest that the Keap1–Nrf2 pathway is activated in pancreatic cancer cell lines through UHRF1‐mediated suppression of Keap1 protein levels, with Keap1 promoter methylation potentially contributing to this." (PMID 26497117, 2016). "Keap1, Nrf2 and the Nrf2 target genes AKR1c1 and GCLC were detected in a panel of five pancreatic cancer cell lines." (PMID 21489257, 2011). "Here, we have demonstrated a lack of consistent correlation between the basal expression levels of Keap1 and Nrf2 mRNA and protein, together with the activity of Nrf2, between pancreatic cancer cell lines, indicating that the Nrf2/Keap1 system may be dysregulated in pancreatic cancer." (PMID 21489257, 2011). "Our study confirmed that miR-532 induces autophagy in pancreatic cancer cells through TWIST1, and the KEAP1/NRF2 pathway may be its downstream target gene." (PMID 37403096, 2023). "To test this, we depleted K‐Ras from pancreatic cancer cells and probed for UHRF1 and Keap1." (PMID 26497117, 2016). "To conclude we can assert that esculetin is a good potential therapeutic agent for pancreatic cancer, where it activates the Nrf2-ARE pathway by binding to KEAP1 protein and ultimately suppresses cancer cell population growth through ROS sensitive transcription factor NFκB." (PMID 27756327, 2016). "In light of recent reports that Nrf2 regulates cancer cell proliferation, and given that the Nrf2/Keap1 system is functional in Suit-2, Miapaca-2 and FAMPAC pancreatic cancer cells, we examined the role of Nrf2 in determining the rate of proliferation of these cells." (PMID 21489257, 2011). "Indeed, Pdx-1-Cre::K-rasLSL-G12D/+::p53LSL-R172H/+::Keap1fl/fl::Nrf2+/+ mice (KPC::Keap1 CKO mice) also exhibited pancreatic atrophy (but no pancreatic tumors; unpublished data)." (PMID 33672789, 2021).
pancreatic cancer (continued). "Moreover, brusatol is unable to lower the expression of Nrf2 mRNA; we believe that brusatol suppresses the Nrf2 pathway through reduced Nrf2 protein expression independent of Keap1 in pancreatic cancer cells as well as in other cancer cells." (PMID 29849873, 2018). "In Cox regression analysis negative membranous Keap1 expression was an independent prognostic factor of pancreatic cancer-related death (hazard ratio 2.66, 95% confidence interval 1.23-5.75) when grade, tumor size and lymph node involvement were taken into the model." (PMID 25879528, 2015). "KPC::Nrf2−/−-mice‒derived pancreatic cancer cell lines (KPCN lines 1 and 2) lack Nrf2, and KPC::K0N0 mice-derived cell lines (K0N0 line 1 and 2) lacked both Nrf2 and Keap1 expression." (PMID 33672789, 2021). "However, UHRF1 levels alone were not sufficient to explain all Keap1 expression patterns in human pancreatic cancers, with occasional high UHRF1 expressers nonetheless expressing detectable Keap1, while some patients lacking UHRF1 also lacked Keap1." (PMID 26497117, 2016).
ovarian carcinoma (37 papers, 2014 to 2025). A malignant neoplasm originating from the surface ovarian epithelium. "A significant association between the ROS suppressant KEAP-1 and ovarian cancer was shown in vitro via genotyping single-nucleotide polymorphisms (SNPs) within KEAP-1 expressed from cancerous epithelial ovarian cells." (PMID 40951130, 2025). "Activating Nrf2 mutations have been described in lung cancer, liver cancer, ovarian cancer, head and neck cancer, kidney cancer, breast cancer, and esophageal cancer, but loss-of-function mutations in KEAP1 and CUL3 also occur frequently." (PMID 39769005, 2024). "Overexpression of miR-141 in ovarian cancer cells also resulted in cisplatin resistance by directly targeting Kelch-like ECH-associated protein 1 (KEAP1)." (PMID 33447132, 2020). "Several studies proved that somatic KEAP1 mutations are present in the tumor tissue of the lung, liver and ovarian cancers." (PMID 32443774, 2020). "A previous study identified heterozygous missense KEAP1 mutations in 5 of 27 (19%) ovarian carcinomas, although frequencies differ across subtypes (29% and 8% in clear cell and serous tumors, resp." (PMID 25114896, 2014). "Our results suggested that overexpressed p62 may protect cells from oxidative damage caused by VK3 through activating Keap1/Nrf2 signaling in ovarian cancer." (PMID 32047536, 2020). "Indeed, a differential expression of Keap1 in tumor tissues compared to healthy adjacent tissues was reported: the KEAP1 gene was inactivated or mutated in cancer tissues of patients with lung, liver, and ovarian cancer." (PMID 39769005, 2024). "Notably, KEAP1 missense or nonsense mutations have also been reported in malignant melanoma and hepatocellular, papillary thyroid, and endometrial carcinomas as well as gall bladder, breast, cervical, and ovarian cancers." (PMID 31097977, 2019). "Previous studies have indicated that APOC1 serves as a prognostic marker for cervical cancer, ovarian cancer, and liver cancer, and it promotes glioblastoma tumorigenesis by inhibiting ferroptosis regulated by the KEAP1/NRF2 and CBS." (PMID 39877420, 2024). "In particular, it has been confirmed that miR-200a-3p/141-3p directly binds to the 3′-UTR of KEAP1, leading to a significant dysregulation of the Nrf2/KEAP1 pathway in both renal tumorigenesis and ovarian cancer cells." (PMID 39769005, 2024). "It was also evidenced that low expression of KEAP1 was correlated with a high mortality in patients with ovarian cancer." (PMID 39769005, 2024). "We also showed a key role of NRF/KEAP1 pathway in regulating NQO1 expression in ovarian cancer cell lines." (PMID 37175546, 2023). "This study highlighted a key role of miR-181d in modulating DDP resistance in ovarian cancer through the OGT/KEAP1/NRF2 axis." (PMID 35453348, 2022). "Recent studies show that the NRF2/KEAP1/ARE pathway plays a key role in many processes involved in the regulation of ovarian cancer progression, proliferation and chemoresistance." (PMID 35453348, 2022). "The abnormal activation of the NRF2/KEAP1 pathway promotes cancer development, metastasis formation, and even resistance to ovarian cancer therapy." (PMID 34371961, 2021). "Also, activation of Nrf2 pathway in ovarian cancer seems to be related to Keap1 mutations within highly conserved domains of Keap1 gene and that Nrf2 may serve as an important therapeutic target for novel drugs capable of preventing or reversing resistance to chemotherapy in ovarian cancer." (PMID 33841137, 2021). "MicroRNA miR-141 was the first-identified miRNA to directly repress KEAP1 levels in ovarian carcinoma cell lines." (PMID 34371961, 2021). "As concerning Keap1, miR-141 was the first miRNA identified to suppress Keap1 levels in ovarian cancer cell lines." (PMID 34573095, 2021). "In this study, we demonstrated that highly expressed p62 in SKOV3/DDP cells activated Nrf2 through interacting with Keap1, which protect ovarian cancer cells from oxidative damage induced by VK3." (PMID 32047536, 2020).